DNMT3A (DNA methyltransferase 3 alpha)
Diseases named in the same sentence as DNMT3A in open-access papers (continued):
Sharing a sentence is not in itself a finding about the gene and the disease.
infarction (2 papers, 2019 to 2025). A localised pathological necrosis of tissue resulting from obstruction of the blood supply usually by a thrombus, an embolus, or vascular torsion. "In an infarction rat model, Dnmt3a expression is increased due tothe lower expression of mir-29a and mir-30c, and these changes correlate withpost-ischemic tissue remodeling." (PMID 31034522, 2019).
injury (2 papers, 2017 to 2022). Damage inflicted on the body as the direct or indirect result of an external force, with or without disruption of structural continuity. "Given that both miR-143 and Dnmt3a are expressed in the DRG neurons, we proposed that miRA-143 might be involved in nerve injury-induced upregulation of Dnmt3a in the DRG under neuropathic pain conditions." (PMID 29170626, 2017).
intracranial aneurysm (2 papers, 2023 to 2025). "The observed association between DNMT3A and a reduced risk of intracranial aneurysm is thus of particular significance, suggesting that DNA methylation, in part mediated by DNMT3A, may play a critical role in IA pathogenesis." (PMID 37742034, 2023).
laryngeal carcinoma (2 papers, 2020 to 2025). Carcinoma that arises from the laryngeal epithelium. "Furthermore, it is the first study investigating expression of DNMT3A and DNMT3B in patients with laryngeal cancer, and it is the first study investigating DNMT1 in locally advanced LSCC." (PMID 40507223, 2025).
leukopenia (2 papers, 2022 to 2024). "Interestingly more patients in the DNMT3A R882 mutant groups showed leukopenia (WBC<2 x 109/L) than the non-R882 groups (31% vs. 24%), and the DNMT3A R882 mutant MDS cases show lower average WBC level than non-R882 mutant cases (mean: 3.0×109/L vs. 4.4×109/L, p=.02)." (PMID 35296003, 2022).
mesothelioma (2 papers, 2018 to 2022). A usually malignant and aggressive neoplasm of the mesothelium which is often associated with exposure to asbestos. "DNMT3A was shown to be overexpressed in mesothelioma cell lines and its expression correlates with worse prognosis in pleural mesothelioma patients." (PMID 36138075, 2022).
microcephaly (2 papers, 2023). A congenital or acquired developmental disorder in which the circumference of the head is smaller than normal for the person's age and sex. "While DNMT3A mutations have been reported in hematologic malignancies, recent studies have linked DNMT3A mutations to developmental growth disorders, such as Tatton-Brown-Rachman syndrome and microcephaly dwarfism." (PMID 37742034, 2023).
paraganglioma (2 papers, 2020 to 2024). A benign or malignant neoplasm arising from paraganglia located along the sympathetic or parasympathetic nerves. "Germline and somatic DNMT3A gain-of-function mutations are also associated with paraganglioma." (PMID 39446312, 2024). "Some HESJAS and paraganglioma mutations are also reported to affect DNA binding by DNMT3A's PWWP." (PMID 39446312, 2024). "Although further studies are needed to support a causal role of DNMT3A variants in paraganglioma, the description of a new DNMT3A alteration in a patient with multiple clinical features suggests a heterogeneous phenotypic spectrum related to DNMT3A germline variants." (PMID 33182397, 2020). "This parallels the hypermethylation of Polycomb-marked facultative heterochromatin observed in HESJAS and paraganglioma and suggests that loss of proper PWWP function causes redistribution of DNMT3A and DNMT3B from H3K36-methylated regions to other parts of the genome." (PMID 39446312, 2024).
pituitary adenomas (2 papers, 2021 to 2022). "It was subsequently concluded that the overexpression of DNMT1 and DNMT3A in cancer was associated with aggressive behavior and hypermethylation status of pituitary adenomas." (PMID 36091786, 2022). "Moreover, research from several sources has identified that hyperexpression of DNMT3A was associated with malignant characteristics of vulvar squamous cell carcinomas, pituitary adenomas, and colorectal cancer (CRC), such as high invasion and migration." (PMID 36091786, 2022). "For instance, DNMT1 and DNMT3a upregulation aggravates the hypermethylation of antitumor genes in human pituitary adenomas." (PMID 34632937, 2021).
renal carcinoma (2 papers, 2021 to 2022). A carcinoma arising from the epithelium of the renal parenchyma or the renal pelvis. "Our results showed that UHRF1 gene expression was correlated with four methyltransferases (DNMT1, DNMT2, DNMT3A, and DNMT3B) in a variety of tumors, and KICH KIRC KIRP was positively correlated with methyltransferase, suggesting that UHRF1 may be an epigenetic driver of renal cancer type." (PMID 35656341, 2022).
sarcopenia (2 papers, 2025). Progressive decline in muscle mass due to aging which results in decreased functional capacity of muscles. "Dnmt3a overexpression was sufficient to reduce the cross-sectional area of fast-twitch (type IIb) myofibers in TA muscle, which is a phenotypic hallmark of sarcopenia." (PMID 40151644, 2025). "N-terminal pro-B-type natriuretic peptide (NT-proBNP) concentration was correlated with DNMT3a mRNA level (r=0.52, p=0.049) only in the group of patients with sarcopenia." (PMID 40034697, 2025). "In the sarcopenia group, two clusters of patients with high and low expression of the DNMT3A gene were observed." (PMID 40034697, 2025). "With reference to the earlier discussion on DNMT3A, its upregulation during T-cell activation leads to inflammation, which may be connected to our other finding—a significant correlation between NT-proBPN level and DNMT3A expression in the sarcopenia group." (PMID 40034697, 2025). "Interestingly, a clear grouping of patients into two clusters within the sarcopenia group by DNMT3a expression level was observed." (PMID 40034697, 2025). "The hypothesis is that genes involved in epigenetic modifications, such as SIRT1, SIRT3, SIRT6, FOXO1, FOXO3A, DNMT3A, and ELAVL1, are critical for the development of sarcopenia and could be used as biomarkers for the diagnosis and monitoring of the disease." (PMID 40034697, 2025).
seminoma (2 papers, 2013 to 2024). A radiosensitive malignant germ cell tumor found in the testis (especially undescended), and extragonadal sites (anterior mediastinum and pineal gland). "In seminomas, expression of DNMT3A or DNMT3B was at a low level, as previously reported." (PMID 38541782, 2024). "DNMT3A was expressed in 3% (2/79) of seminomas and 36% (37/102) of synovial sarcomas, while DNMT3B was expressed in 33% (27/79) of seminomas and 5% (5/102) of synovial sarcomas." (PMID 38541782, 2024). "Seminomas and the seminoma-like cell line TCam-2 seem to utilize the replication dependent maintenance DNA methylation pathway since they display high DNMT1 expression and low/absent DNMT3A/B/L levels." (PMID 24386123, 2013).
synovial sarcoma (2 papers, 2024 to 2025). "We first investigated whether the genes that regulate DNA methylation (DNMT1, DNMT3A, DNMT3B, TET1, TET2, TET3) are misexpressed, mutated, or amplified in synovial sarcoma." (PMID 40299558, 2025). "In synovial sarcomas, a positive association between expression of PRAME and DNMT3A was identified." (PMID 38541782, 2024).
temporal lobe epilepsy (2 papers, 2016 to 2025). A localization-related (focal) form of epilepsy characterized by recurrent seizures that arise from foci within the temporal lobe, most commonly from its mesial aspect. "Increased expression of DNMT1 and DNMT3A has been demonstrated in epileptic model and patients with temporal lobe epilepsy." (PMID 40534269, 2025). "On the contrary, it has been shown that Dnmt1 and Dnmt3a expression is increased in the anterior temporal neocortex in human temporal lobe epilepsy." (PMID 27505431, 2016).
testicular cancer (2 papers, 2020 to 2022). A primary or metastatic malignant neoplasm that affects the testis. "Previous evidence showed that DNMT3a was a target of miR-199a-3p in testicular cancer." (PMID 33365310, 2020).
testicular germ cell tumor (2 papers, 2019 to 2021). A germ cell tumor arising from the testis. "miR-1291 targets DNA methyltransferases (Dnmt3a, Dnmt3b) that are involved in (de novo) histone methylation, genomic imprinting, X-chromosome inactivation, and testicular germ cell tumors due to exposure to alkylphenols." (PMID 34199666, 2021).
Thrombocytosis (2 papers, 2023 to 2024). Increased numbers of platelets in the peripheral blood. "The VAF of DNMT3A mutations was significantly lower in thrombocytosis cases compared with their matched controls (P = 0.018; Suppl." (PMID 36698617, 2023). "However, a near-significant protective effect of DNMT3A mutations on the survival of thrombocytosis cases was found (P = 0.057)." (PMID 36698617, 2023).
thyroid cancer (2 papers, 2020 to 2026). "To note, AML, thyroid cancer and PPGL show the lowest tumor mutational burden amongst all neoplasia (n = 10–14), something that indicates a low number of passenger variants and stresses the relevance for tumor development of mutated genes, such as DNMT3A." (PMID 33182397, 2020). "Moreover, COSMIC reports only one DNMT3A variant affecting the microcephalic dwarfism-mutated residue Asp333 and it affects an anaplastic thyroid carcinoma, further supporting the relevance of the PWWP domain in thyroid cancer." (PMID 33182397, 2020).
varicocele (2 papers, 2021 to 2024). A condition characterized by the dilated tortuous veins of the spermatic cord with a marked left-sided predominance. "One proposition is that this increasemay be related to the dual role played by DNMT3A andDNMT3B enzymes, acting as methyl-transferases innormal conditions as well as dehydroxymethylases instress conditions, like varicocele." (PMID 34455713, 2021). "However,percentage of DNMT3A (fertile: 48.34 ± 6.35 vs.varicocele, 65.42 ± 3.9, P=0.02) and DNMT3B positivesperm (fertile: 64.31 ± 4.8 vs. varicocele: 76.61 ± 3.1,P=0.03) were significantly higher in varicocele comparedto fertile group." (PMID 34455713, 2021). "Therefore,this secondary function displayed by DNMT3A andDNMT3B under oxidative stress conditions like the stateof varicocele may physiologically play significant rolesin the gene expression via epigenetic regulation." (PMID 34455713, 2021). "In a study by Rashidi and colleagues, the expression of DNMT3A and DNMT3B was elevated in 35 men with varicoceles at both the mRNA and protein levels." (PMID 38392299, 2024). "Our findings indicated that in contrast to the percentage of DNMT1 positive sperm, the mean percentagesof DNMT3A and DNMT3B positive sperm weresignificantly higher in varicocele group than fertilegroup." (PMID 34455713, 2021). "Incontrast to DNMT1, expression and percentage of DNMT3A and DNMT3B at RNA and protein levels were significantlyhigher in the varicocele group compared to the fertile group (P<0.05)." (PMID 34455713, 2021). "Hypo-methylation and high expressionof DNMT3A and DNMT3B at both mRNA and proteinlevels may be part of a compensative mechanism of thecell in varicocele state or play a dual role in oxidativestress condition." (PMID 34455713, 2021). "Localization of DNMT1, DNMT3A andDNMT3B enzymes were assessed in over 1000 spermfrom five pooled samples of only fertile individuals byfluorescence microscopy, not varicocele group." (PMID 34455713, 2021). "This might suggest thataltered DNA methylation in varicocele state is not dueto aberration of DNA maintenance, but it is rather dueto altered activity of DNMT3A and DNMT3B enzymesinvolved in de novo DNA methylation." (PMID 34455713, 2021). "Negative correlationswere observed between percentage of sperm abnormalmorphology with percentage of DNMT1, DNMT3Aand DNMT3B positive sperm in varicocele group.Percentage of DNMT3A positive sperm also had negativesignificant correlation with percentage of sperm abnormalmorphology in fertile group." (PMID 34455713, 2021).
acute monocytic leukaemia (1 paper, 2025). "In acute monocytic leukaemia, DNMT3a, with a high mutation frequency, was found to be associated with poor prognosis and was expected to be a novel molecular marker for diagnostic and prognostic evaluation." (PMID 39990668, 2025).
age (1 paper, 2025). A temporal measurement of the time period elapsed since an identifiable point in the life cycle of an organism. "In contrast, variants in genes most common in age-related CH, DNMT3A and TET2, were relatively infrequent (3 of 144, 2.1%, and 4 of 144, 2.8%, respectively) and occurred at median age of 59 years (range 47–70), generally in line with their occurrence in the general population." (PMID 40179146, 2025).
alcoholism (1 paper, 2018). "Contrary to the previous report on cell line study; our animal experiments revealed that, DNMT1 and DNMT3a protein levels were significantly decreased in brain tissue of mice under alcoholism and exercise restored their levels back to normal." (PMID 29581524, 2018). "The results revealed that, DNMT1 and DNMT3a protein levels were significantly decreased under alcoholism when compared to the control group." (PMID 29581524, 2018).
allergic asthma (1 paper, 2023). A asthma with a basis in a pathological type I hypersensitivity reaction. "A previous study used macrophage exosome membranes to encapsulate Dnmt3a, and this strategy was successful in treating allergic asthma." (PMID 37275919, 2023).
ameloblastic carcinoma (1 paper, 2021). A rare, cytologically malignant ameloblastoma that may metastasize. "This study aimed to describe the immunohistochemical expression of DNMT1, DNMT3A, DNMT3B, and H3K9ac in the dental follicle (DF), ameloblastoma (AME), and ameloblastic carcinoma (AC), correlating these expressions with the recurrence and aggressive behavior in ameloblastoma." (PMID 35048062, 2021). "Therefore, we aimed to investigate DNMT1, DNMT3A, DNMT3B, and H3K9ac immunohistochemical expression in the most prevalent and locally aggressive benign odontogenic tumor, ameloblastoma, and compare this with its malignant counterpart, ameloblastic carcinoma (AC)." (PMID 35048062, 2021).
autoimmune encephalitis (1 paper, 2021). Inflammation of the brain secondary to an immune response triggered by the body itself. "For Blimp-1+ eTregs in the CNS of experimental autoimmune encephalitis-diseased animals it was elucidated that Blimp-1, here maintained by proinflammatory STAT-1 signaling, ensures Foxp3 expression by inhibition of the methyltransferase Dnmt3a." (PMID 35069572, 2021).
bacteremia (1 paper, 2024). "Furthermore, transcriptional profiles correlated with lower IL-10 cytokine level and heterozygous DNMT3A A/C genotype, both of which have been associated with reduced risk of PB outcome in human MRSA bacteremia." (PMID 38846955, 2024). "In the present study, we examined the transcriptome, DNMT3A genotype and IL-10 proteome of whole peripheral blood to differentiate immune response pathways associated with RB versus PB outcomes in clinical MRSA bacteremia." (PMID 38846955, 2024). "To better understand the mechanism linking IL-10 levels to outcomes in MRSA bacteremia, we determined the relationship between identified hub genes in the B and T cell enriched signaling modules (ME7 and ME2 respectively), IL-10 cytokine levels and DNMT3A genotype." (PMID 38846955, 2024).
brain tumor (1 paper, 2022). "Using the public database TCGA, we analyzed the expression of genes studied in the present study, including PRRX1, PROM1, and DNMT3A, to investigate possible correlations between the expression of these genes, the brain tumor grade, and patient prognosis." (PMID 34214250, 2022).
cardiopulmonary diseases (1 paper, 2023). "Accumulation of somatic mutations in DNMT3A and other CHIP genes in hematopoietic cells and cardiovascular tissues creates an inflammatory environment that promotes cardiopulmonary diseases, even in the absence of hematologic disease." (PMID 37947606, 2023).
Castleman disease (1 paper, 2023). Castleman disease (CD) is a benign lymphoproliferative disorder that may present as a localized or multicentric form. "In Castleman disease, improper ETS1, PTPN6, TGFBR2, DNMT3A, and PDGFRB genes cause the appearance of symptoms." (PMID 36766791, 2023).
cerebral infarction (1 paper, 2022). An ischemic condition of the brain, producing a persistent focal neurological deficit in the area of distribution of the cerebral arteries. "In the MCAO animal model, DNA methylation is elevated in neurons located around the cerebral infarction at 24 h after MCAO and reperfusion, which is attributed to the increased activation of DNMT3a." (PMID 36142283, 2022).
cerebrovascular diseases (1 paper, 2020). "This analysis may not only be useful as a novel diagnosis biomarker of neurodegenerative and cerebrovascular diseases but it may also help to distinguish patients with PD (with lower 5hmC levels and no changes in DNMT3a expression) from AD or DV." (PMID 32210102, 2020).
chronic asthma (1 paper, 2021). An asthma that is characterized by the development of persistent airway inflammation and recurrent attacks of breathlessness and wheezing, which vary in severity and frequency. "Immunohistochemical analysis confirmed that de novo methyltransferase DNMT3a and DNMT3b were significantly decreased in chronic asthma compared with the control group, and was especially expressed in bronchial epithelium." (PMID 35058921, 2021). "We measured the expression of DNA methyltransferase and found that the expression of DNMT3a and DNMT3b were significantly decreased in chronic asthma while DNMT1 did not have any statistical difference." (PMID 35058921, 2021).
chronic obstructive pulmonary disease (1 paper, 2023). A chronic and progressive lung disorder characterized by the loss of elasticity of the bronchial tree and the air sacs, destruction of the air sacs wall, thickening of the bronchial wall, and mucous accumulation in the bronchial tree. "Our findings are consistent with the notion that CH with TET2 mutations is different from CH with DNMT3A or ASXL1 mutations as indicated by some clinical studies, for example, CH with TET2 mutations has been linked to chronic obstructive pulmonary diseases but not CH with DNMT3A mutations." (PMID 37083525, 2023).
clear cell carcinoma (1 paper, 2012). "Expression of DNMT3a protein was 69.1% in serous carcinoma, which was higher than that of mucinous carcinoma (33.3%) and clear cell carcinoma (50%) (Fisher’s exact test, P = 0.027)." (PMID 22768205, 2012).
co-infection (1 paper, 2019). "However, most TUJ1 +iN cells in the CreGfp condition were still expressing low levels of DNMT3A (white arrows) despite co-infection with CreGfp." (PMID 30644360, 2019).
colon adenocarcinoma (1 paper, 2021). "We identified EHMT2/G9a (Hazard ratio (HR): 2.2, p = 0.0036) and DNMT3A (HR: 1.9, p = 0.047) overexpression to be significantly associated with shorter RFS in colon adenocarcinomas (COAD)." (PMID 33323965, 2021).
colorectal adenoma (1 paper, 2017). An adenoma that arises from the colon or rectum. "Dnmt3a suppresses K-Ras-driven lung tumor progression, whereas Dnmt3b is pro-tumorigenic in APC-deficient colorectal adenomas." (PMID 28425913, 2017).
cryptorchidism (1 paper, 2020). The failure of one or both testes of a male fetus to descend from the abdomen into the scrotum during the late part of pregnancy. "Sperm deformities and cryptorchidism were observed, which was associated with raised Dnmt levels (Dnmt1, Dnmt3a, Dnmt3b)." (PMID 32398147, 2020).
cutaneous squamous cell carcinoma (1 paper, 2017). "Thus, inhibition of PPAR-γ could be a potential new therapy for cutaneous squamous cell carcinomas harboring low levels of Dnmt3a." (PMID 28425913, 2017).